IL6 (interleukin 6)
Diseases named in the same sentence as IL6 in open-access papers (continued):
Sharing a sentence is not in itself a finding about the gene and the disease.
colon carcinoma (continued). "Likewise human CRC exhibits increased IL-6 levels in both serum and tumor biopsies and has been also found to positively correlate with tumor load in colon cancer patients." (PMID 28881611, 2017). "Downregulation of MUC2 and overexpression of IL-6 were found in colon cancer." (PMID 28725043, 2017). "The MUC2 protein plays an important role in IL-6 signaling during colon cancer metastasis." (PMID 28725043, 2017). "In addition, IL-6 was found to induce STAT3 phosphorylation in RAB3C-overexpressing colon cancer cells, thus promoting migration." (PMID 28784136, 2017). "Interleukin-6 is a proinflammatory cytokine with pleiotropic functions in regulating not only different aspects of immune responses but also the growth and differentiation of different types of cancer cells, including breast, liver, and colon cancers." (PMID 28856117, 2017). "To determine whether MUC2 silencing increases IL-6 secretion in HT-29 colon cancer cells, we incubated HT-29-derived cell clones with MSs for 48 h and determined the IL-6 concentration in the resulting supernatants by ELISA." (PMID 28725043, 2017). "Colon cancer cells stimulate macrophages to produce IL-6, which activates STAT3 in tumor cells." (PMID 28725043, 2017). "Peritoneal fluids collected at surgery initiation and after surgery were evaluated for their effect on migration potential of human colon cancer cells using an in vitro scratch assay and on TNF-α, IL-1β, IL-6, and IL-10 levels using bead-based fluorokine-linked multianalyte profiling." (PMID 26819599, 2016). "Our results suggest that inhibition of IL-6 may enhance chemosensitivity of colon cancers with overactive STAT3 to platinum agents." (PMID 27006530, 2016). "We confirmed that colon carcinoma cell lines express IL-6 and IL-6R." (PMID 26673628, 2015). "IL-6 induced a STAT3-mediated IL-10 production in colon tumor cells is also reported." (PMID 26556872, 2015). "So decrease in IL6 expression possibly has some role in therapeutic aspect of colon cancer." (PMID 26556872, 2015). "In addition, the enhancement of REG Iα promoter activity by IL-6 was reported also in colon cancer cells and in salivary ductal cells." (PMID 25767811, 2015). "Fifteen genes (DUSP2, INFGR1, IL6, IRF2, JAK2, MAP3K10, MMP1, NFkB1A, NOS2A, PIK3CA, SEPX1, SMAD3, TLR2, TYK2, and VDR) were significantly associated with colon cancer mortality at the <0.05 level; an additional 15 genes had gene PARTP values between 0.05 and 0.10." (PMID 25541970, 2014). "In addition, studies have found that the downstream target of the TLRs signaling pathway, such as Interleukin-6, 8 (IL-6, IL-8), are inflammatory cytokines that play a role in colon cancer." (PMID 25547486, 2014). "Therefore, in the current study we investigated the impact of 1,25D3, tumor necrosis factor alpha (TNFα), and interleukin (IL)-6 on CaSR expression in a differentiated (Caco2/AQ) and in a moderately differentiated (Coga1A) colon cancer cell line." (PMID 24176760, 2014). "S100A10 may be involved in releasing pro-inflammatory cytokines, such as interleukin-6, which has been suggested to promote cell growth and apoptosis-escape in colon cancer." (PMID 24851084, 2014). "Fifteen genes (DUSP2, INFGR1, IL6, IRF2, JAK2, MAP3K10, MMP1, NFkB1A, NOS2A, PIK3CA, SEPX1, SMAD3, TLR2, TYK2, and VDR) were associated with colon cancer mortality (PARTP <0.05); JAK2 (PARTP = 0.0086), PIK3CA (PARTP = 0.0098), and SMAD3 (PARTP = 0.0059) had the strongest associations." (PMID 25541970, 2014). "Moreover, IL-6 has been shown to promote the growth of colon cancer epithelial cells in a cell culture system in vitro." (PMID 25547486, 2014). "MUC2 silencing also increased interleukin (IL)-6 secretion by colon cancer cells." (PMID 25322805, 2014). "Crosstalk between TGFα and IL-6 has been demonstrated in an inflammatory colon cancer model." (PMID 25547486, 2014).
colon carcinoma (continued). "Whether the increase in AMPKα we observed is due to elevations in IL-6, changes in nutrient uptake secondary to colon tumor load, or some combination of the two is currently unclear." (PMID 23589074, 2013). "IL-6 has been shown to lead to STAT3 activation in colon cancer." (PMID 24098947, 2013). "Increased intratumoral IL-6 and possibly IL-11 expression suggested that dietary iron may promote colonic tumor development via a Stat3-mediated pathway." (PMID 24223168, 2013). "Increased intratumoral IL-6 and possibly IL-11 expression suggested that Stat3 activation may contribute to the development of dietary iron induced-colonic tumors." (PMID 24223168, 2013). "In the present study, we demonstrated that 25-HC increased IL-8 and IL-6 release from airway epithelial cells, which was supported by previous reports on the effect of 25-HC on IL-8 release in a human macrophage lineage and colon carcinoma cell line." (PMID 22849850, 2012). "However, we found no change in leukocyte infiltration in tumors over-expressing IL-17F despite the elevated levels of IL-6 and TNFα in vitro, and unaltered cytotoxic immune cell frequencies in mesenteric lymph nodes of colon tumor bearing Il-17f−/− mice." (PMID 22509371, 2012). "More recently, it has been characterized as an inflammatory cytokine that is implicated in several pathologic intestinal conditions (e.g. colon cancer and inflammatory bowel disease) likely through induction of IL-1b, IL-6, IL-8, IL-12, TNFα, and other pro-inflammatory cytokines." (PMID 22829946, 2012). "We found that VEGF correlated with IL-1 and IL-6 exclusively in cachectic colon cancer patiens." (PMID 20920199, 2010). "IL-6 itself has been shown to exhibit the upregulation of HLA class I molecules and certain tumor-associated antigens such as carcinoembryonic antigen (CEA) in colon carcinoma cells, as does IFN-γ." (PMID 19497133, 2009). "In colonic cancer, a cross talk between IL-6 and TGF-β has been suggested, and in intestinal epithelial cell culture, TGF-β1 may inhibit IL-6 expression." (PMID 19450258, 2009). "We therefore reasoned that IL-6, when released from rather undifferentiated colon carcinoma cells, may aid tumour progression by a paracrine-induced proliferation of still differentiated neoplastic cells." (PMID 18205904, 2008). "In addition, IL-6 increases invasiveness of colon cancer cells and likely promotes secondary tumour formation through its angiogenic potency." (PMID 18205904, 2008). "This relationship has been reported in some studies on colon carcinoma, where they suggest that in certain colon carcinoma cells, the production of IL-10 derived from the tumor is directly regulated by the systemic or local production of pro-inflammatory cytokines, such as IL-6 and IFN-γ." (PMID 40722593, 2025). "Elevated systemic inflammation is driven by chronic release of proinflammatory cytokines (e.g., IL-6, TNF-α), recruitment of neutrophils and macrophages, and expansion of Th1/Th17 responses—features linked to tumor progression and immune dysregulation in colon cancer." (PMID 41008758, 2025). "Moreover, the results of regression analysis showed that the risk of death in elderly patients with colon cancer increased with the increase of serum TNF-α and IL-6 levels, indicating that TNF-α and IL-6 are independent risk factors for poor prognosis in elderly patients with colon cancer." (PMID 37430251, 2023). "IL-6 is also involved in signaling and immunoregulatory cascades by binding to its receptor (IL-6R) on gp130-positive cells – thereby activating the transcription factor signal transducer and activators of transcription 3 (STAT3) and increasing the risk of colon cancer." (PMID 36792680, 2023).
colon carcinoma (continued). "The observation that IL-6 is strongly upregulated in the inflammatory environment of ApcMin/+ mice and colon cancer patients in males and females may therefore explain the lack of sex-related differences detected in the influence of CB2 on colon cancer severity in our ApcMin/+ model." (PMID 36835468, 2023). "OH2 could safely eliminate malignant ascites of colon cancer and convert the cold immune microenvironment by inducing a remarkably regional cytokine storm in ascites, mainly IL‐6, in the early stage of antitumor immune responses beyond directed oncolytic virotherapy." (PMID 35510373, 2022). "However, for completeness, it should also be mentioned that despite its predominantly pro-tumorigenic function, IL-6 has been described as an important activator of the macrophage-mediated phagocytosis of colon tumor cells, driving the required cytoskeleton rearrangement." (PMID 36428508, 2022). "Moreover, GNAI1 could act as a tumor suppressor in colon cancer by regulating the IL6 signaling pathway." (PMID 35669499, 2022). "Thus, our findings suggest that the inhibitory effects of exercise on colon cancer cell proliferation may be partly driven by IL‐6‐induced regulation of DNA damage and repair." (PMID 35213038, 2022). "Our results show that LPE is able to inhibit the IL-6-dependent cell migration and invasiveness associated with the up-regulation of MMP-2 expression levels and that these effects are correlated to the STAT3 phosphorylation in human primary T88 and T93 colon cancer cells." (PMID 34885656, 2021). "High levels of pSer153 RKIP are induced by IL-6 and H. pylori infection in colon and gastric cancers, respectively, and are associated with a poor prognosis in stage II colon cancer patients and little to no response to therapy for patients with multiple myeloma." (PMID 34944867, 2021). "In the present study, we attempted to find out whether water-soluble polysaccharide isolated from A. heterophyllus can influence the viability of human colon carcinoma cells and change pro- (IL-1β, IL-6) and anti-inflammatory (IL-10) cytokines and nitric oxide (NO) produced by them." (PMID 31947694, 2020). "Therefore, we next aimed to assess the efficacy of the resveratrol derivatives in inhibiting NFκB activity by utilizing a dual-luciferase reporter assay for NFκB target gene (IL-6) in two colon cancer cell lines (HCT-116 and SW-480) and a normal mouse intestinal cell line (ModeK)." (PMID 32847114, 2020). "In addition, we examined the effects of this treatment on the IL-6-mediated activity of HCT116 human colon cancer cells, including cell proliferation and apoptosis, STAT3 phosphorylation levels and transcriptional activity, and the multiple target genes of the IL-6/STAT3 signalling pathway." (PMID 33082817, 2020). "Thus, MUC2 expression in colon cancer may play an important role in the IL6-dependent signaling pathway." (PMID 28725043, 2017). "In addition, treatment with BAY-117082 (NF-κB inhibitor) and a monoclonal antibody against IL-6 significantly suppress tumor growth in xenografts of breast, prostate and colon cancer cells, indicating the importance of these pathways in tumor cell transformation." (PMID 28416734, 2017). "Furthermore, given the effects of MUC2 on IL-6 secretion, its targeting may represent a potentially useful strategy to treat colonic carcinomas." (PMID 25322805, 2014). "Therefore, MUC2 expression by colon cancer cells alters IL-6 secretion." (PMID 25322805, 2014). "Therefore, in the present study, we studied the impact of 1,25D3, TNFα, and IL-6 on transcriptional and translational regulation of CaSR in two colon cancer cell lines with different proliferation and differentiation properties, mimicking different tumor stages." (PMID 24176760, 2014).
colon carcinoma (continued). "The increased secretion of IL-6 by MUC2-knockdown tumor cells and enhanced tumor growth observed in the present study suggest that the protective mechanisms of MUC2 in colon cancer may be associated with its effects on suppressing the IL-6/STAT3 signaling pathway." (PMID 25322805, 2014). "Neutralizing IL-6 in the CT26 colon cancer model restored microbial balance and eubiosis, while elevated serum LBP and IL-6 emerged as robust biomarkers that can stratify prognosis and guide diagnosis and therapy for CC." (PMID 41514616, 2025). "Elevated expression of IL‐6 and activation of the JAK2/STAT3 pathway are tightly correlated with the progression of malignancies, including HCC, colon cancer, bc, NSCLC, and NPC." (PMID 41316520, 2025). "We co-cultured NIH3T3 with human colon cancer cells (DLD1) in the presence of L-OHP and measured mouse and human IL-6 levels." (PMID 40718440, 2025). "Loigolactobacillus coryniformis NA-3 induces NO, IL-6, TNF-α, and ROS production in colonic TAMs and significantly inhibits the proliferation of colonic tumor cells." (PMID 40873588, 2025). "Inhibition of CYP19A1 resulted in the downregulation of PD-L1, IL-6 and TGF-β expression in colon cancer cells, thereby enhancing the tumor-killing ability of CD8+ T cells." (PMID 41415563, 2025). "Studies have shown that CAFs transformed by cancer cells within the TME secrete interleukin-6 and enhance STAT3 signaling in colon cancer cells, promoting the production of CSCs and further driving the progression of malignant tumors." (PMID 41194856, 2025). "In colon cancer, under hypoxic conditions, CAF-derived IL-6 activates STAT3 signaling to promote tumor progression or induce drug resistance via a HIF-1a/miR-338-5p/IL-6 feedback loop." (PMID 39251966, 2024). "When colon cancer was induced with AOM/DSS, the expression of inflammation-related genes such as IL-1β, IL-6, and TNF in the blood increased, and the expression of inflammatory cytokines was confirmed in the serum of mice." (PMID 38338927, 2024). "This interplay between IL-1β and IL-6 in colon cancer progression was corroborated by findings from GEPIA and TIMER, with similar observations in a study involving African American colon cancer patients." (PMID 38671854, 2024). "In our investigation using the AOM/DSS colon cancer model, we explored the interplay between PXR and the IL‐6/STAT3 pathway." (PMID 39495702, 2024). "Consistent with our results, stevioside played an anti-inflammatory and immunomodulatory role in the human colon carcinoma cell line (Caco-2) by potentially suppressing lipopolysaccharide-induced pro-inflammatory cytokine TNF-α, IL-1β, and IL-6 productions." (PMID 37237936, 2023). "We found that CYP19A1 expression level was significantly positively correlated with PD-L1, IL-6 and TGF-β levels in the TCGA colon cancer dataset." (PMID 37055842, 2023). "Mechanistically, when miR-155-5p is delivered from M2 macrophages to colon cancer cells via exosomes, it disrupts the ability of ZC3H12B to reduce the stability of IL-6, resulting in immune evasion and tumor formation." (PMID 37981718, 2023). "Second, we uncovered for the first time that CYP19A1 inhibition downregulated PD-L1, IL-6 and TGF-β expression in colon cancer cells, and thereby enhanced the tumor-killing ability of CD8+ T cells." (PMID 37055842, 2023). "In colon cancer cells, the overexpression of miR-155-5p and IL-6, along with the reduced expression of zinc-finger-type-containing 12B (ZC3H12B), promotes the progression of colon cancer." (PMID 37981718, 2023). "Exogenous supplementation of estradiol increased IL-6 and TGF-β expression in HCT116 and HT29 colon cancer cells." (PMID 37055842, 2023). "Our results demonstrate that 24 weeks of 150 min/wk of moderate-intensity aerobic exercise reduce hs-CRP and IL6 by 35.4% and 29.6% among stage III colon cancer survivors." (PMID 38148846, 2023).
colon carcinoma (continued). "Previous study have shown that cytokine levels are significantly increased in the serum of colon cancer patients, especially for TNF-α and IL-6." (PMID 37430251, 2023). "Multiple inflammatory markers, such as tumor necrosis factor α (TNF-α), interleukin-6 (IL-6), and vascular endothelial growth factor (VEGF) have demonstrated prognostic value in patients with colon cancer." (PMID 37430251, 2023). "Several cytokines, including interleukin-6 (IL-6), tumor necrosis factor-alpha (TNF-α), and transforming growth factor-beta (TGF-β), have been identified as important regulators of colon cancer development and progression." (PMID 37465677, 2023). "The reduction of MMP-1 and MMP-3 expression was reported to correlate with the inflammatory cytokine IL-6, signal transducer and activator of transcription (STAT), and the AP-1 (IL-6/STAT-1/AP-1) axis in colon cancer." (PMID 36839884, 2023). "Next, we verified the factors derived from tumor cells in HT29 and HCT116 colon cancer cells, and comfirmed that CYP19A1 inhibition significantly reduced PD-L1, IL-6, and TGF-β expression in tumor cells." (PMID 37055842, 2023). "Inflammatory factors, like COX-2 and IL-6, jointly form the inflammatory network in gastric cancer, and the function of COX-2 in colon tumor metastasis has been confirmed in vivo." (PMID 37153547, 2023). "Inflammatory events were evoked by TNF-α in human colon cancer LIM1215 cells, and induced IL-6 mRNA levels were evaluated." (PMID 37743524, 2023). "CB2 may act by modulating the levels of IL-6 under low inflammatory conditions, while CB2−/− females, which have increased IL-6 levels even under non-inflammatory conditions, are at a higher risk for colon cancer in the steady-state because of the IL-6-induced upregulation of MDSCs." (PMID 36835468, 2023). "When P14AS was overexpressed in colon cancer cell lines, enhanced TNF-NF-κB signaling pathway activity was observed together with increases in IL6 and IL8 expression." (PMID 38041015, 2023). "IPA also showed increased EMT and IL-6 signaling, similar to the findings of GSEA, along with increase in HIF1α and colon cancer metastasis signaling, suggesting that MAC had a worse prognosis." (PMID 35267605, 2022). "Our study found that loss of GOLPH3 attenuated the IL-6 induced phosphorylation of STAT3 in colon cancer cells, while the overexpression of GOLPH3 enhanced STAT3 phosphorylation in the presence of IL-6." (PMID 35372504, 2022). "Moreover, reanalysis of single cell RNA-seq data of colon cancer revealed that TAMs increased activation of NO-related pathways, including protein nitrosylation and NO-mediated signal transduction, as well as inflammatory cytokine signalling, such as IL-6 and TNF-α." (PMID 35660630, 2022). "Because cancer cells depend on aerobic glycolysis for increased growth and proliferation, treatment with human recombinant IL‐6 stimulates aerobic glycolysis and promotes the proliferation of SW480 and SW1116 colon cancer cells." (PMID 35791509, 2022). "Anti-IL-6 neutralizing antibody, JAK2 inhibitor and STAT3 gene knockout in mouse cancer cells reduced BMF and BMF-CM induced colon cancer cell spheroid formation." (PMID 36591515, 2022). "In a mouse model, GNAI1 and GNAI 3 suppressed DSS-plus-azoxymethane-induced colon tumor development, whereas the expression of GNAI2 in CD11c+ cells and interleukin-6 (IL6) in CD4+/CD11b+ dendritic cells appeared to promote these effects." (PMID 35743732, 2022). "EMT and IL-6 signaling were also increased in IPA, in addition to colon cancer metastasis signaling, hypoxia-inducible factor 1-alpha (HIF1α) signaling, and the tumor microenvironment pathway." (PMID 35267605, 2022). "IL-6 deficient mice have been reported to exhibit reduced tumor growth and metastasis, and increased IFN-γ producing CD8 T cells; despite improving tumorigenesis, IL-6-/- mice showed enhanced PD-L1 expression on murine CT26 colon cancer cells which could be mitigated by anti-PD-L1 immunotherapy." (PMID 34504657, 2021).